SETD2 (SET domain containing 2, histone lysine methyltransferase)
Diseases named in the same sentence as SETD2 in open-access papers (continued):
Sharing a sentence is not in itself a finding about the gene and the disease.
medulloblastoma (4 papers, 2018 to 2024). A malignant, invasive embryonal neoplasm arising from the cerebellum. "The medulloblastoma described in our cohort belongs to the Sonic Hedgehog genetic group, and has two point mutations in SETD2 with reported VAFs of 5% and 6%." (PMID 30419952, 2018). "In total, 26 SETD2 mutations were seen among the 22 tumors with one medulloblastoma having 3 SETD2 missense mutations." (PMID 30419952, 2018). "Data from the TCGA database also showed SETD2 mutations in pilocytic astrocytomas, an oligodendroglioma, and medulloblastomas." (PMID 30419952, 2018). "However, our results include a broader range of CNS tumor types, and demonstrate SETD2 truncating mutations in atypical meningiomas and pilocytic astrocytomas, as well as missense mutations in a choroid plexus papilloma and a medulloblastoma." (PMID 30419952, 2018). "However, it is likely SETD2 mutant tumors were also present in the posterior fossa as mutations were seen in 5 medulloblastomas and 2 pilocytic astrocytomas, tumors which both have a strong association with the posterior fossa." (PMID 30419952, 2018). "Notably, SETD2 mutations occurred exclusively in medulloblastoma group-4 tumours (P < 1 × 10−4)." (PMID 32025007, 2020). "Inactivation of SETD2 in medulloblastoma significantly decreased gene expression (P = 0.002)." (PMID 32025007, 2020). "Prior studies of medulloblastomas did not detect mutations in SETD2 suggesting SETD2 mutations are rare in these tumors." (PMID 30419952, 2018). "Somatic analysis of the disease-involved sample was consistent with non-WNT/non-SHH medulloblastoma, including ZMYM3 p.Ala217fs and SETD2 p.Glu1582Lys variants, in addition to copy number gain of chromosome 7, loss of chromosome 8 and 13, and isochromosome 17q." (PMID 36980535, 2023). "However, we identified a recurrent CNA that spanned SETD2 in medulloblastomas that lacked known drivers, indicating that restricting hypothesis testing to missing-driver cases can improve power if undiscovered genes are enriched in such tumours." (PMID 32025007, 2020).
pulmonary arterial hypertension (4 papers, 2021 to 2025). Pulmonary arterial hypertension (PAH) is a group of diseases characterized by mean pulmonary artery pressure >20 mmHg and elevated pulmonary arterial resistance leading to right heart failure. "They further suggested inhibition of SETD2/METTL14 activity as a possible strategy for treatment of pulmonary artery hypertension in clinical settings." (PMID 35061109, 2022). "In pulmonary arterial hypertension (PAH), SETD2-mediated H3K36me3 modification upregulates METTL14 expression, leading to enhanced m6A deposition." (PMID 41164187, 2025). "Collectively, these results demonstrated that SETD2 mediates H3K36me3 and METTL14 mediated m6A RNA modification contribute to hypoxia-induced pulmonary arterial hypertension in mice." (PMID 33658391, 2021). "This novel information partially clarified that SETD2 mediates H3K36me3 and METTL14 mediated m6A RNA modification contribute to hypoxia-induced pulmonary arterial hypertension in mice." (PMID 33658391, 2021).
Sotos syndrome (4 papers, 2015 to 2023). Sotos syndrome is a rare multisystemic genetic disorder characterized by a typical facial appearance, overgrowth of the body in early life with macrocephaly, and mild to severe intellectual disability. "The mutations in SETD2 cause a novel overgrowth condition in human, leading to Sotos syndrome, which was typically characterized by macrocephaly." (PMID 37502307, 2023).
systemic mastocytosis (4 papers, 2021 to 2025). Systemic mastocytosis (SM) comprises a heterogeneous group of rare acquired and chronic hematological malignancies that are related to an abnormal proliferation of mast cells in tissue, including bone marrow, with or without skin involvement. "We have recently reported that most patients with advanced systemic mastocytosis (AdvSM) and some with indolent or smoldering SM display H3K36Me3 deficiency as a result of a reversible loss of SETD2 due to reduced protein stability." (PMID 36894973, 2023). "Taken together, our results point to SETD2/H3K36me3 deficiency as a mechanism, already identified by our group in systemic mastocytosis, that is reversible, druggable, and BCR::ABL1‐independent, able to cooperate with BCR::ABL1 in driving genetic instability in CML." (PMID 40275711, 2025). "Inappropriate expression of SETD2 and resulting errors in H3K36 trimethylation have been linked to various types of malignancies, for example human breast cancer, clear cell renal cell carcinoma (cRCC), and systemic mastocytosis (SM)." (PMID 34576219, 2021). "Finally, decreased or absent SETD2 protein expression and reduced levels of H3K36 trimethylation have been observed in systemic mastocytosis (SM), with low expression of SETD2 correlating with disease aggressiveness." (PMID 38036730, 2023).
thymic carcinoma (4 papers, 2017 to 2023). Thymic carcinoma (TC) is a type of thymic epithelial neoplasm characterized by a high malignant potential. "In thymic carcinomas, mutations were found in genes involved in the histone modification pathway, including BAP1 (6%), SETD2 (11%), ASXL1 (4%), and in chromatin remodeling genes, such as SMARCA4 (4%)." (PMID 38201593, 2023). "Recurrent mutations in chromatin remodeling genes were reported in thymic carcinomas, but no mutation in chromatin remodeling genes (SETD2, KDM6A, MLL2, and MLL3) was found in thymic adenocarcinoma." (PMID 28506304, 2017). "Genes involved in histone modification (BAP1, 13%; SETD2, 11%; ASXL1, 4%), chromatin remodelling (SMARCA4, 4%), and DNA methylation (DNMT3A, 7%; TET2, 4%; WT1, 4%) were frequently mutated in thymic carcinomas, but not thymomas." (PMID 35884448, 2022).
chondroblastoma (3 papers, 2015 to 2022). A benign, chondroid-producing, well-circumscribed, lytic neoplasm usually arising from the epiphysis of long bones. "What about for K36M mutants in chondroblastoma—are SETD2 or other K36 methyltransferases similarly dominantly blocked for function?" (PMID 25773741, 2015).
colitis (3 papers, 2022 to 2025). Inflammation of the colon. "Particularly in SETD2-deficient colitis, the therapeutic effect of targeting deliver Grem1 is significantly higher than that of DSS-induced colitis." (PMID 39990215, 2025). "We assessed the consequences of Setd2 loss in ISCs in colitis by challenging Setd2f/f and Setd2ISC-KO mice with 2.5% DSS after tamoxifen administration." (PMID 39990215, 2025). "Collectively, these results demonstrate that loss of Setd2 in ISCs aggravates DSS-induced colitis in mice." (PMID 39990215, 2025). "Together, the data indicate that loss of Setd2 in Treg cells prevents them from inhibiting pathogenic T cell expansion during colitis in vivo." (PMID 36463230, 2022). "We showed that Setd2-deficient Treg cells had increased fate conversion in CD45RBhighT cell-induced colitis and during homeostatic expansion in Rag2–/– mice." (PMID 36463230, 2022). "Besides, we also explored that loss of Setd2 in ISCs exacerbates DSS-induced colitis in mice and targeted delivery of Grem1 by AT-MSCs shows higher efficacy in Setd2-deficient colitis." (PMID 39990215, 2025). "The data suggest that in TNBS colitis, Setd2-deficient Treg cells are defective in suppressing Th1 but not Th17 responses, which may be controlled by the retained inhibitory function of RORγt+ Treg cells." (PMID 36463230, 2022). "Nevertheless, when transferred together with CD45RBhigh pathogenic T cells into Rag2–/– mice, splenic Setd2-deficient Treg cells had a reduced capacity to suppress colitis compared to control Treg cells in vivo, as indicated by the greater body weight loss and shortened colons of recipient mice." (PMID 36463230, 2022). "In our study, we firstly elucidated that loss of Setd2 reduces ISCs proliferation and exacerbates DSS-induced colitis in mice." (PMID 39990215, 2025). "Our previous studies have reported that SETD2 modulates oxidative stress to attenuate experimental colitis." (PMID 39990215, 2025). "The data raise a possibility that other mechanisms in addition to preventing fate conversion of Treg cells could contribute to Setd2-supported Treg sustentation in CD45RBhighT cell-induced colitis." (PMID 36463230, 2022).
colon cancer (3 papers, 2023). "Researchers have demonstrated that Setd2 deletion accelerates colon carcinogenesis and progression through conditional knockout and spontaneous colon cancer mouse models, thus highlighting the critical role of Setd2 in CRC development." (PMID 37697409, 2023).
endometrial cancer (3 papers, 2022 to 2023). Primary or metastatic malignant neoplasm involving the endometrium (mucous membrane that lines the endometrial cavity). "Wilcoxon rank-sum tests showed that the SETD2 mut + group had a significantly higher MSIsensor score than that the SETD2 mut- group in endometrial carcinoma, colorectal adenocarcinoma, and stomach adenocarcinoma." (PMID 37479966, 2023). "Additionally, in endometrial carcinoma, colorectal adenocarcinoma, and stomach adenocarcinoma, SETD2 should be considered when dMMR is detected by immunohistochemistry." (PMID 37479966, 2023). "Third, although preclinical data has shown that SETD2 deficient cells have impaired MMR and HRR, we identified unimpaired HRR in endometrial carcinoma, colorectal adenocarcinoma, and stomach adenocarcinoma; this may be explained by possible synthetic lethality between impaired HRR and impaired MMR." (PMID 37479966, 2023). "However when exploring the potential effects of a SETD2 mutation on homologous recombination pathways, we observed a decreased HRD score in the SETD2 mut + group compared to the SETD2 mut- group in endometrial carcinoma, colorectal adenocarcinoma, and stomach adenocarcinoma." (PMID 37479966, 2023).
enteropathy-associated T-cell lymphoma (3 papers, 2019 to 2025). An uncommon mature T-cell lymphoma of intraepithelial lymphocytes. "SETD2 (SET-domain-containing 2), a methyltransferase responsible for H3 lysine 36 trimethylation (H3K36me3), is mostly silenced in enteropathy-associated T-cell lymphoma (EATL), as well as monomorphic epitheliotropic intestinal T-cell lymphoma (MEITL)." (PMID 35326620, 2022).
fetal macrosomia (3 papers, 2020 to 2022). "Furthermore, circ-SETD2 was implicated in placental growth, with elevated circ-SETD2 in placentae of patients with fetal macrosomia." (PMID 35562943, 2022). "In the present study, we provided evidence that the involvement of circ-SETD2 (circRNA_103345) in placenta increased in women with macrosomia." (PMID 32626774, 2020). "The result identified that circ-SETD2 was highly expressed in the placenta of the patients with fetal macrosomia compared with healthy donors." (PMID 32626774, 2020). "With the circ-SETD2 expression in the placenta of both fetal macrosomia patients and healthy donors now clearly quantified, we sought to clarify the effects of circ-SETD2 on placental development by using an in vitro trophoblast-like HTR8/SVneo cell culture system." (PMID 32626774, 2020). "The aberrant high levels of circ-SETD2 and PTEN were found in the fetal macrosomia patients' group." (PMID 32626774, 2020). "Finally, we examined the levels of circ-SETD2, miR-519a, and PTEN in placentas of fetal macrosomia patients and healthy donors." (PMID 32626774, 2020).
inflammatory bowel disease (3 papers, 2023 to 2025). A spectrum of small and large bowel inflammatory diseases of unknown etiology. "This agrees with recent research into inflammatory bowel disease, which found that SETD2 loss in the gut led to excessive ROS." (PMID 39921567, 2025). "Thus, we sought to elucidate the therapeutic effect of targeting delivery of Grem1 and IL-10 in SETD2-deficient and DSS-induced inflammatory bowel disease." (PMID 39990215, 2025).
microcephaly (3 papers, 2023). A congenital or acquired developmental disorder in which the circumference of the head is smaller than normal for the person's age and sex. "It is worth noting that some patients bearing SETD2 c.5218C>T mutation showed microcephaly (11/11), short stature (3/9), low weight (3/9), which were contrary to the typical features caused by other SETD2 mutations." (PMID 37025455, 2023). "Germline mutations in IGF1R are associated with pre- and post-natal growth retardation and microcephaly and combined investigations of the epigenetic and transcriptional effects of germline SETD2 LoF and codon 1740 mutations could provide candidate genes for aspects of SETD2-associated NDDs." (PMID 37166351, 2023). "In addition to the potential role of ASH1L in the control of brain size postnatally, clinical studies suggest that mutations in either NSD1, NSD2, SETD2, or SETD5 have also been implicated in microcephaly." (PMID 36845425, 2023).
non-small cell lung carcinoma (3 papers, 2019 to 2025). A group of at least three distinct histological types of lung cancer, including non-small cell squamous cell carcinoma, adenocarcinoma, and large cell carcinoma. "Moreover, acquired loss-of-function mutations in SETD2 enable metastatic non-small cell lung cancer to resist to cisplatin." (PMID 30922329, 2019).
Obesity (3 papers, 2023 to 2025). Accumulation of substantial excess body fat. "Here we examined the effect of obesity from a HFD on paternal SETD2 expression and methylation in sperm, and embryos at the blastocyst stage and during subsequent development, to determine the alteration of SETD2 in paternal intergenerational and transgenerational inheritance." (PMID 37598138, 2023). "Moreover, obesity can regulate the mutation of oncogenes, such as Kirsten rat sarcoma virus (KRAS), epidermal growth factor receptor (EGFR), SET domain-containing 2 protein (SETD2), and BRCA1-associated protein 1 (BAP1), which also increases the risk of cancer development." (PMID 40863244, 2025).
ovarian carcinoma (3 papers, 2020 to 2023). A malignant neoplasm originating from the surface ovarian epithelium. "All responders with ovarian cancer had received prior platinum therapy and PARPi therapy, except for one patient with a granulosa cell ovarian tumor with a SETD2 LOF alteration." (PMID 37277454, 2023).
Anxiety (2 papers, 2023 to 2025). Intense feelings of nervousness, tension, or panic often arise in response to interpersonal stresses. "Mutations to the Set2-Rpb1 interaction (SRI) domain of SETD2, which is responsible for substrate recognition, resulted in increased anxiety-like behavior and reduced dendritic arborization and axon length in mice." (PMID 36845425, 2023).
Arthritis (2 papers, 2021 to 2022). Inflammation of a joint. "In our previous research, we showed that the SETD2, an epigenetic regulator is upregulated during OC differentiation and after induction of arthritis and SETD2’s regulatory mechanisms." (PMID 36307395, 2022). "Together these findings for the first time revealed that SETD2 mediated epigenetic regulation of Wnt5a plays a critical role in osteoclastogenesis and induced arthritis." (PMID 34663428, 2021). "We found that SETD2 and WNT5a were upregulated during osteoclast differentiation and after induction of arthritis." (PMID 34663428, 2021). "To define the role of SETD2 in the WNT5a signaling in the context of osteoclastogenesis, we exploited two different models: in vitro osteoclast differentiation, and K/BxN serum-induced arthritis model." (PMID 34663428, 2021). "Furthermore, using a K/BxN serum-induced arthritis (RA) model, we shed light on the role of SETD2 in the expression Wnt signaling molecules." (PMID 34663428, 2021). "After in vitro confirmation, we sought to determine whether the mechanistic regulation of SETD2 is persistent in induced arthritis model." (PMID 34663428, 2021).
B-cell lymphoma (2 papers, 2025). "Except for SETD2, no other alterations in genes associated with B-cell lymphomas were noted." (PMID 40901224, 2025).
collecting duct carcinoma (2 papers, 2020 to 2024). "In the rare RCC category, collecting duct carcinoma (CDC) harbors mutations in NF2, SETD2, SMARCB1, FH, and CDKN2A genes while renal medullary carcinoma is distinctively characterized by loss of SMARCB1/INI1 tumor suppressor protein." (PMID 32575429, 2020). "Alterations in SETD2, NF2, ARID1, and MLH1 were identified in collecting duct carcinoma samples, although none were significantly associated with gene signatures." (PMID 38652565, 2024).
COVID-19 (2 papers, 2021). A disease caused by infection with severe acute respiratory syndrome coronavirus 2. "In module 1, NSD1, KMT2E, and SETD2, which are histone lysine methyltransferases involved in cell development and differentiation, were expressed at lower levels in COVID-19 patients." (PMID 33936072, 2021). "The mono-CD16+ cell population in COVID-19 patients showed reduced transcription levels of genes related to lysine degradation (NSD1, KMT2E, and SETD2) and elevated transcription levels of genes involved in OXPHOS (ATP6V1B2, ATP5A1, ATP5E, and ATP5B), which may inhibit M2-like polarization." (PMID 33936072, 2021). "In mono-CD16+ cells in COVID-19 patients, we found reduced lysine degradation (downregulation of NSD1, KMT2E, and SETD2) and enhanced OXPHOS, which may inhibit M2 macrophage polarization and differentiation through the cAMP and MAPK signaling pathways or the PI3K, AKT and mTOR signaling pathways." (PMID 33936072, 2021).
epilepsy (2 papers, 2022 to 2024). A brain disorder characterized by episodes of abnormally increased neuronal discharge resulting in transient episodes of sensory or motor neurological dysfunction, or psychic dysfunction. "To date, a syndrome with a “pure” association between CM1 and epilepsy has not been identified in spite of the recent description of new syndromes, such as the PTEN hamartoma tumor or the SETD2 neurodevelopmental one, which include CM1 and epilepsy." (PMID 36294502, 2022).
immune deficiency (2 papers, 2021 to 2023). "As only four patients with SETD2 mutations experienced recurrent otitis and the onset age was younger than 5 years old, no solid evidences support that Luscan-Lumish syndrome is associated with immune deficiency or another disease is co-occurring in the patient we reported." (PMID 37025455, 2023).
invasive breast carcinoma (2 papers, 2019 to 2024). A carcinoma that infiltrates the breast parenchyma. "We identified KMT2D, SETD1A and SETD2, included in the lysine methyltransferase activity function, as linked with poor prognosis in invasive breast cancer." (PMID 30990809, 2019).
malignant pleural mesothelioma (2 papers, 2016 to 2023). A malignant neoplasm that arises from mesothelial cells in the pleura and shows a diffuse growth pattern.